GSDMD (gasdermin D)
Diseases named in the same sentence as GSDMD in open-access papers (continued):
Sharing a sentence is not in itself a finding about the gene and the disease.
Salmonella Infections (12 papers, 2019 to 2026). Infections with bacteria of the genus SALMONELLA. "In contrast, during Salmonella infection, cell lysis occurred independently of both GSDMD and GSDME, suggesting the involvement of alternative lytic mechanisms." (PMID 42044191, 2026). "Overall, these results indicate that GSDMD plays an important role in mediating inflammasome responses during Salmonella infection of human macrophages." (PMID 40162563, 2025). "Consistent with previous research, we found that Salmonella infection significantly enhanced both protein and mRNA expressions of GSDMD and the protein expression of GSDMD-N." (PMID 35163196, 2022). "Importantly, infected GSDMD-/- cells failed to undergo substantial cell death, in contrast to infected WT cells, indicating that GSDMD facilitates cell death during Salmonella infection." (PMID 40162563, 2025). "Similarly to Salmonella infection, LPS transfection only caused cell death in IFNγ-primed HeLa and was completely abrogated by deletion of CASP4 or GSDMD." (PMID 32581219, 2020). "Whether the Caspase-8/GSDMD pathway is also involved in Salmonella infection deserves deep investigation." (PMID 33384666, 2020). "Beyond these connections, in cells lacking pyroptosis via GSDMD-deficiency, caspase-1 can cleave caspase-3 and Bid to promote apoptotic cell death in response to inflammasome triggers such as LPS priming and poly(dA:dT) transfection, or during Salmonella infection." (PMID 35563804, 2022). "In THP-1 macrophages, GSDME mediates IL-1β release and limited pyroptosis in response to nigericin treatment and Salmonella infection, as well as pyroptosis in the absence of GSDMD." (PMID 37279255, 2023). "Despite abundant expression of multiple Gasdermins in mammalian gut tissue, we here find using a mouse line lacking all mouse Gasdermins at once that only Gasdermin D provides protection against oral Salmonella infection." (PMID 37988464, 2023). "Deletion of CASP4 or GSDMD did not alter bacterial invasion, but abrogated Salmonella-induced IFNγ-dependent cell death, confirming that Salmonella infection of HeLa cells activates the non-canonical inflammasome in an IFNγ-dependent manner." (PMID 32581219, 2020). "In THP-1 cells lacking GSDMD, GSDME allows the release of IL-1β in response to nigericin, Val-boroPro, or Salmonella infection, though limited cell death was observed with endogenous GSDME expression levels in these cells." (PMID 35563804, 2022). "In line with this, a recent study showed that caspase‐1, in the absence of Gasdermin D, cleaves tBID and induces SMAC release in the context of Salmonella infection." (PMID 34931711, 2022).
steatosis (12 papers, 2020 to 2025). Increased lipid within the cytoplasm of cells. "In addition, the decreased expression of ASC, caspase-1 p20, and GSDMD suppressed the hepatocyte pyroptosis pathway, which improved the inflammation, steatosis, and cell damage associated with pyroptosis, thereby alleviating NASH." (PMID 38547097, 2024). "Liver samples of NASH patients and rodent models of NASH showed increased expression of caspase 1, gasdermin D (GSDMD) and inflammasome components compared to the simple steatosis stage." (PMID 33548031, 2021). "In conclusion, our research results show that BSP-1 can improve liver injury and steatosis caused by MASLD in both in vitro and in vivo experiments, this effect may be attributed to the regulation of the pyrother-related NLRP3/caspase-1/GSDMD pathway." (PMID 40626309, 2025). "Deficiency of GSDMD in mice typically leads to relief of the NASH phenotype, including reduction of inflammation, attenuation of steatosis, and amelioration of fibrosis, while overexpression of GSDMD augments liver inflammation and steatosis following feeding of an MCD diet." (PMID 35350750, 2022). "In HCC patients, pir-hsa-216911 was highly expressed in HCC tumor samples with steatosis, suppressing TLR4 expression and inhibiting GSDMD activation." (PMID 39824843, 2025). "Therefore, H2-rich medium inhibited the expression of inflammatory cytokines, and targeted GSDMD and GSDME to alleviate OA-induced steatosis in HepG2 cells." (PMID 40860880, 2025). "GSDMD and its pyroptosis-inducing fragment GSDMD-N were upregulated in liver tissues of human NAFLD/NASH; MCD diet-fed GSDMD−/− mice exhibited decreased severity of steatosis and inflammation compared with wild type littermates." (PMID 32849904, 2020). "Therefore, BSP-1 plays a role in alleviating MASLD by preventing steatosis, inflammation, and pyroptosis, which may be relate to the inhibition of NLRP3/caspase-1/GSDMD signaling pathway." (PMID 40626309, 2025).
alcohol addiction (11 papers, 2020 to 2025). "GSDMD inhibitors include disulfiram (used to treat alcohol addiction), C202-2729, teriflunomide, and necrosulfonamide, which inhibits GSDMD pore formation, pyroptosis and IL-1β release in cell and mouse models." (PMID 41280719, 2025). "The FDA-approved drug DSF, which is used to treat alcohol addiction, was recently shown to inhibit GSDMD pore formation." (PMID 39024551, 2024). "The FDA-approved drug disulfiram (DSF), which is used to treat alcohol addiction, was recently shown to inhibit GSDMD pore formation." (PMID 36797275, 2023). "A recent study also showed that dithiamine, an FDA-approved drug for the treatment of alcohol addiction, inhibited the formation of membrane pores by covalently modifying Cys191/Cys192 in GSDMD." (PMID 34484243, 2021). "GSDMD was newly found as a pyroptosis executor and serves as a potent target for pyroptosis related diseases; and it is found that disulfiram, a drug used to treat alcohol addiction, could inhibit pyroptosis by blocking GSDMD pore formation." (PMID 35669106, 2022). "Moreover, the FDA-approved drug DSF, which is used to treat alcohol addiction, has been recently shown to inhibit GSDMD pore formation." (PMID 35350176, 2022).
liver diseases (11 papers, 2020 to 2025). "In liver diseases, the excessive activation of GSDMD significantly exacerbates liver injury, with its activation primarily involving immune cells and hepatocytes." (PMID 39994107, 2025). "In heart and liver diseases, GSDMD expression is markedly elevated in cardiomyocytes and hepatocytes, contributing to the regulation of pathological processes." (PMID 39994107, 2025). "It is worth noting that the role of GSDMD in different liver diseases is largely controversial and highly correlated with liver pathologies." (PMID 35972273, 2022). "The role of GSDMD in autoimmune liver diseases or other liver diseases is complex and intriguing, deserving deep investigation." (PMID 35972273, 2022). "GSDMD, which serves as the executioner of pyroptosis, has been reported to be involved in several liver diseases." (PMID 35972273, 2022). "Recently, increasing evidence have suggested a critical role of GSDMD-mediated pyroptosis in liver diseases." (PMID 32194416, 2020). "NLRP3 inflammasome activation may lead to GSDMD-driven pyroptosis, which plays a key role in the occurrence and development of liver diseases." (PMID 34630100, 2021). "Notably, pyroptosis is a key pathogenetic factor in the development of NAFLD, and suppression of inflammasome-dependent GSDMD-mediated cell pyroptosis could attenuate hepatic injury in liver diseases." (PMID 34239622, 2021). "By specifically and precisely targeting key molecules in the pyroptosis pathway, such as NLRP3 and GSDMD, pathological processes of liver diseases can be alleviated without compromising the body’s immune defense mechanisms." (PMID 39917567, 2025).
nasopharyngeal carcinoma (11 papers, 2021 to 2025). A carcinoma arising from the nasopharyngeal epithelium. "For example, taxol treatment causes GSDMD-mediated pyroptosis in nasopharyngeal carcinoma, whereas suppression of pyroptosis has been proposed to be associated with taxol resistance in nasopharyngeal carcinoma." (PMID 33941231, 2021). "For example, the caspase-1/GSDMD-mediated pyroptosis pathway plays a crucial role in Taxol resistance in nasopharyngeal carcinoma." (PMID 37156816, 2023). "For instance, caspase-1/GSDMD mediated pyroptosis is connected with Taxol resistance in nasopharyngeal carcinoma." (PMID 37156816, 2023). "Moreover, in Taxol-treated nasopharyngeal carcinoma cells, autophagy was activated, and pyroptosis was suppressed, which inhibited the caspase-1/gasdermin D (GSDMD) pathway and inflammasome activation." (PMID 36158216, 2022). "Another study examined the role of three proteins, Nod-like receptor protein 3 (NLRP3), cysteine-aspartic acid protease 1 (Caspase-1), and Gasdermin D (GSDMD), in nasopharyngeal carcinoma (NPC)." (PMID 39744516, 2025). "In a study focusing on nasopharyngeal carcinoma (NPC), it was discovered that caspase-1 inhibition and GSDMD knockout could induce a Taxol-resistant phenotype in vitro and in vivo and that autophagy could negatively regulate the canonical pathway of pyroptosis in NPC cells." (PMID 35198448, 2022). "Tan IIA targets miR-125b/gasdermin D (GSDMD) and miR-145/caspase 1, which induces apoptosis of nasopharyngeal carcinoma (NPC) cells (HK1 cells) and cervical carcinoma cells (HeLa cells), respectively." (PMID 36172186, 2022).
pancreatic cancer (11 papers, 2021 to 2025). "In various types of cancer, such as breast and pancreatic cancers, the activation of GSDMD has been associated with both the tumor's immune microenvironment and the effectiveness of treatments." (PMID 40008397, 2025). "This leads to a significant increase in ROS, activation of caspase-1 and GSDMD, and ultimately induces pyroptosis in pancreatic cancer cells." (PMID 39994107, 2025). "These AV-EVLPs can inhibit pancreatic cancer progression by increasing mitochondrial ROS release through the activation of caspase-1/3/7/9 and GSDMD/E-mediated pyroptosis in Panc-1 cells." (PMID 40604924, 2025). "LCL161 18 is a pyrrolidine-thiazole-containing compound that triggers pyroptosis in pancreatic cancer, leukemia, and multiple myeloma cells by activating caspase-1 and GSDMD." (PMID 39316325, 2025). "Inhibition of GSDMD cleavage by adding specific inhibitor blocked DH-induced cell death, indicating DH potentially induced pyroptosis in pancreatic cancer cells." (PMID 39358349, 2024). "In PANC-1, a pancreatic cancer cell line, DH induced the release of mitochondria DNA (mtDNA) and led to inflammasome-mediated gasdermin D (GSDMD) activation, ultimately activating pyroptosis and inhibiting pancreatic tumor growth in vivo." (PMID 39358349, 2024). "Intracellular levels of GSDMD are significantly increased during the early stages of pancreatic cancer development, but further investigation is required to determine if GSDMD levels are elevated in bodily fluids or the systemic circulation." (PMID 38002346, 2023). "Recent studies have highlighted the role of pyroptosis in tumorigenesis, with widespread amplification of pyroptosis-related genes (PRGs) such as AIM2, NLRP3, GSDMD, and IL-18 observed in pancreatic cancer." (PMID 38002346, 2023). "In pancreatic cancer, GSDMD-mediated pyroptosis is a result of multi-organ interactions." (PMID 39994107, 2025). "Likewise, trametinib 78 is a dual kinase inhibitor used to induce the pyroptotic pathways in pancreatic cancer and melanoma through caspase-1/GSDMD activation." (PMID 39316325, 2025). "Moreover, GSDMD activation and function were conserved in human CD4+ T cells and associated with favorable prognosis and improved response to anti–PD-1 immunotherapy in colonic and pancreatic cancer." (PMID 40759573, 2025). "These composites inhibited glucose and glutamine uptake of pancreatic cancer cells through the released BAY-876 and V-9302, leading to nutrition deprivation and oxidative stress, activating caspase 1 and GSDMD, and finally, inducing pyroptosis." (PMID 40375976, 2025). "In summary, RP-6306 not only facilitates GSDMD cleavage but also robustly activates a network of upstream signaling pathways including NLRP3, AIM2, and Caspase-1 in pancreatic cancer cells." (PMID 40664640, 2025). "Using confocal microscopy to interrogate tumor tissues, GSDMD activation in CD4+ T cells within both human colonic and pancreatic tumor tissues was further confirmed by anti–GSDMD-N staining." (PMID 40759573, 2025). "We identified GSDMB, GSDMD, and GSDME as the top three genes expressed in pancreatic cancer." (PMID 39358349, 2024).
rheumatoid arthritis (11 papers, 2020 to 2026). A chronic, systemic autoimmune disorder characterized by inflammation in the synovial membranes and articular surfaces. "Previous studies have shown an enhanced expression of GSDMD in the serum of patients with rheumatoid arthritis (RA) and emphasized pyroptosis in association with RA." (PMID 33013384, 2020). "The fact that TNF-induced lethality shows a GSDMD dependency, where GsdmdD88A mice succumb with faster kinetics compared to WT counterparts, and Gsdmd−/− mice are protected, highlights GSDMD as a possible therapeutical candidate for TNF-associated diseases such as rheumatoid arthritis." (PMID 35455985, 2022). "Besides, the studies have shown that IL-37 alleviates TNF-induced pyroptosis of rheumatoid arthritis fibroblast-like synoviocytes by inhibiting the NF-κB/GSDMD signaling pathway." (PMID 40704967, 2025). "This study found that HCQ significantly inhibited the expression of pyroptosis markers GSDMD and NLRP3 in microglia, a mechanism similar to HCQ's inhibition of cell death pathways in rheumatoid arthritis." (PMID 39694827, 2024). "For example, serum of rheumatoid arthritis (RA) patients could induce GSDMD-dependent pyroptosis in monocytes, which was promoted by PTX3 and C1q." (PMID 36057687, 2022).
asthma (10 papers, 2022 to 2026). "salidroside and its analogs can target GSDMD to inhibit asthma exacerbation in ozone-induced inflammation environments." (PMID 42093379, 2026). "Through experimentation and multiomics approaches, gasdermin D (GSDMD) was identified as a key gene in exacerbating asthma under ozone exposure." (PMID 42093379, 2026). "The clinical relevance of this pathway is underscored by findings of upregulated caspase-4 and GSDMD in bronchial biopsies from severe asthma patients with recurrent viral exacerbations." (PMID 41394843, 2025). "Supporting this, elevated markers of pyroptosis are detected in asthma patients, and GSDMD activation correlates with increased airway hyperresponsiveness (AHR) in experimental models, suggesting its contribution to disease severity." (PMID 41394843, 2025). "Single-cell transcriptomics of severe asthma biopsies has revealed epithelial cells co-expressing GSDMD and MLKL, correlating with neutrophilia and impaired steroid signaling, indicating PANoptosis as a key contributor to refractory phenotypes." (PMID 41394843, 2025). "Furthermore, scRNA-seq and virtual knockout revealed that GSDMD exerts a pro-inflammatory effect on the asthma microenvironment." (PMID 42093379, 2026). "Evidence from severe asthma patients reveals upregulated caspase-4 and GSDMD expression." (PMID 41394843, 2025). "In severe, refractory asthma, this interplay may necessitate complex co-targeting strategies (e.g., simultaneously inhibiting GSDMD and the necroptosis mediator MLKL), adding layers of complexity to therapeutic development." (PMID 41394843, 2025). "Similarly, inhibiting Gasdermin D, the terminal execution protein of pyroptosis, may reduce airway epithelial damage in patients with asthma." (PMID 40620703, 2025). "Additionally, CAD and CAD-contained serum attenuated the up-regulated expressions of Bax, Cleaved caspase-3, NLRP3, ASC, Cleaved caspase-1, GSDMD-N, IL-18, IL-1β, TLR3, p-P65, p-IκBα, and IRF3 but increased Bcl-1 and GSDMD levels in the asthma mice and LPS-induced 16HBE cells, respectively." (PMID 36213326, 2022). "Therefore, GSDMD may serve as a potential therapeutic target against asthma." (PMID 38849380, 2024). "Notably, cytoplasmic viral components can also activate the non-canonical inflammasome pathway, engaging caspase-4/5 in humans (caspase-11 in mice), which cleaves GSDMD independently of NLRP3, triggering further epithelial barrier disruption and exacerbating viral-induced asthma flare-ups." (PMID 41394843, 2025). "In addition, the protein expression levels of NLRP3, caspase-1, cleaved caspase-1, GSDMD, GSDMD-N, IL-18, and IL-1β were increased, indicating that MUC1, TLR4/MyD88/NF-κB pathway, and NLRP3-induced pyroptosis are involved in the pathogenesis of asthma." (PMID 37880668, 2023).
familial Mediterranean fever (10 papers, 2020 to 2025). Familial Mediterranean fever (FMF) is an autoinflammatory disorder characterized by recurrent short episodes of fever and serositis resulting in pain in the abdomen, chest, joints and muscles. "Deletion of GSDMD in MefvV726A/V726A, a mouse model of familial Mediterranean fever (FMF), an autoimmune disease driven by mutations in the gene Mefv, leads to normal growth and rescues inflammation." (PMID 37612410, 2023). "Infection of familial Mediterranean fever knock-in macrophages with Clostridium difficile resulted in the expression of a chimeric familial Mediterranean fever-associated Mefv (V726A) pyrin-induced pyroptosis and GSDMD-mediated IL-1BIL-1B secretion in vitro." (PMID 34858408, 2021). "GSDMD-mediated pyroptosis plays a crucial role in the pathogenesis of familial Mediterranean fever in mouse models." (PMID 34858408, 2021). "In familial Mediterranean fever (FMF), knock-in macrophages expressing chimeric Mefv (V726A) pyrin exhibit pyroptosis and GSDMD-mediated IL-1β secretion upon infection with Clostridium difficile." (PMID 39994107, 2025).
Hepatic steatosis (10 papers, 2020 to 2025). Steatosis is a term used to denote lipid accumulation within hepatocytes. "As expected, overexpression of NRF2 improved liver steatosis in diet‐induced obese mice, while inhibiting pyroptosis and inflammation markers, including cle‐Caspase1, GSDMD, N‐GSDMD, Pro‐IL1β and IL1β." (PMID 39995148, 2025). "Furthermore, GSDMD knockout improved hepatic steatosis, the inflammatory response and fibrosis in NASH model mice." (PMID 40398602, 2025). "Overall, our findings provide insight into the mechanism by which PcP extracts alleviate hepatic steatosis, highlighting the potential significance of modulating the NLRP3/Caspase‐1/GSDMD pathway in the context of pyroptosis." (PMID 39055201, 2024). "The results demonstrated that the administration of PcP extract effectively decreased dyslipidemia and hepatic steatosis, which coincided with a decrease in hepatic pyroptosis through modulation of the NLRP3/Caspase‐1/GSDMD pathway in liver tissues." (PMID 39055201, 2024). "A previous study showed that CBD alleviated hepatic steatosis and oxidative stress and significantly decreased the expression of NF-κB, NLRP3, ASC, procaspase-1, caspase-1 p20, GSDMD, and cleaved GSDMD both in vivo and in vitro." (PMID 36016562, 2022).
lung adenocarcinoma (10 papers, 2021 to 2024). A carcinoma that arises from the lung and is characterized by the presence of malignant glandular epithelial cells. "Interestingly, higher GSDMD expression was related to more severe carcinogenesis with a larger tumor size and more progressive tumor metastasis, which was indicative of a poor prognosis for lung adenocarcinoma." (PMID 38016064, 2023). "The inhibition of GSDMD attenuates cell proliferation and activates caspase-3 and poly (ADP-ribose) polymerase (PARP) to initiate intrinsic apoptosis in the lung adenocarcinoma cell lines PC9 and H1975 and the squamous lung cancer cell line H1703." (PMID 34522213, 2021). "Patients with lung adenocarcinoma (LUAD), but not in squamous cell carcinoma (LUSC), presenting high GSDMD protein levels experience shorter survival, which indicates that GSDMD is an independent prognostic factor for LUAD." (PMID 35896522, 2022).